ADAM17 (ADAM metallopeptidase domain 17)
Diseases named in the same sentence as ADAM17 in open-access papers (continued):
Sharing a sentence is not in itself a finding about the gene and the disease.
COVID-19 (continued). "Our multivariable MR analysis suggested a direct causal role of ADAM17 (extracellular domain) on critical COVID-19 (OR = 1.09; 95% CI: 1.01–1.17) after accounting for body mass index (BMI), which is a risk factor suggested to have a causal effect on severe COVID-19." (PMID 37958866, 2023). "Collectively, these genetic associations may contribute to the understanding of ADAM17 and its potential implications in relation to severe COVID-19." (PMID 37958866, 2023). "Therefore, the relationship between cardiovascular disease and COVID-19 is critically dependent on the loss of membrane ACE2 by ADAM17-mediated proteolytic cleavage." (PMID 38077924, 2023). "Our primary MR analysis showed that a 1 SD increase in genetically determined circulating ADAM17 (extracellular domain) was associated with an increased risk of developing critical COVID-19 (odds ratio (OR) = 1.26, 95% CI: 1.03–1.55, inverse-variance weighted (IVW) method)." (PMID 37958866, 2023). "For example, the participants in the GWAS of ADAM17 included an enriched number of cancer patients and cancer may be associated with COVID-19 severity." (PMID 37958866, 2023). "Moreover, since ADAM17 is overexpressed in diabetic patients, the high risk of COVID-19 complications in these patients can be due to the inhibition of AAT activity by diabetic-dependent glycosylation." (PMID 35163482, 2022). "Here, we evaluated the ADAM17 inhibitory effects of cordycepin (CD), thymoquinone (TQ), and N6, N6-dimethyladenosine (m62A), on cancer cells and predicted the anti-COVID-19 potential of the three compounds and their underlying signaling pathways by network pharmacology." (PMID 36558177, 2022). "The ACE2/ADAM17/TMPRSS2 interplay has been suggested as the main risk factor for COVID-19." (PMID 35887687, 2022). "ADAM17 is an emerging therapeutic target for several pulmonary pathologies, and its inhibition has been shown to prevent the pathophysiological neutrophilia associated with COVID-19." (PMID 36298651, 2022). "The detrimental consequences of ADAM17 activity in COVID-19 may be linked to TNF release and its contribution to the “cytokine storm,” a feature of the disease that leads to vascular hyperpermeability, multiorgan failure and death." (PMID 33579029, 2021). "Consequently, the inhibition of ADAM17 could have a dual therapeutic effect: a modulation of the cytokine storm associated with COVID-19 and an attenuation of SARS-CoV-2 infection." (PMID 39292373, 2025). "Mechanisms underlying increased levels of sACE2 in severe COVID-19 are unclear but could be related to increased ADAM-17 activity, hyperinflammation (elevated levels of plasma IL-1beta, IL-6 and TNF-alpha), increased renin–angiotensin system activity, and lung cell injury." (PMID 38892098, 2024). "Therefore, by employing Mendelian randomization (MR), we aimed to investigate if there is a causal relationship between circulating ADAM17 (cytoplasmic and membrane-bound domains) and the risk of severe COVID-19, using the latest genome-wide association studies (GWAS) of ADAM17 and COVID-19." (PMID 37958866, 2023). "Interestingly, ADAM-17 is associated with the pathogenesis of COVID-19." (PMID 37372128, 2023). "Therefore, the occurrence of specific comorbidities associated with RAS imbalance mediated by ACE2/ADAM17 along with specific genetic factors mainly associated with TMPRSS2 expression could be decisive for the clinical outcome of COVID-19." (PMID 33117379, 2020). "For ADAM-17, healthy individuals showed the highest levels, while patients with severe COVID-19 had the lowest values." (PMID 40003732, 2025). "Our findings confirm previous studies showing higher expressions of TMPRSS2, ADAM-17, and IL-17A in healthy individuals compared to COVID-19 patients, recovered, and vaccinated individuals." (PMID 40003732, 2025).
COVID-19 (continued). "Preclinical data suggest that pharmacological inhibition of ADAM17 reduces pulmonary inflammation, diminishes leukocyte infiltration, and improves the neutrophil-to-lymphocyte ratio—an established marker of COVID-19 severity." (PMID 41050403, 2025). "During SARS-CoV-2 infection, ADAM17 contributes to COVID-19 pathogenesis by promoting the shedding of angiotensin-converting enzyme 2 (ACE2), thereby disrupting its protective signaling axis." (PMID 41050403, 2025). "Based on the MGH-OLINK-COVID-19 dataset, the ADAM-17 substrate z-score was overall (day 0, day 3 and day 7 altogether) higher in patients with severe COVID-19 (OR = 1.45 per SD 95% CI 1.09–1.93, p = 0.01) adjusting for comorbidities, age, and BMI categories." (PMID 38892098, 2024). "In non-COVID-19 infected individuals, the fold difference between ADAM-17 and ACE2 gene expression is higher in the lungs compared to that of other tissues." (PMID 38892098, 2024). "We found that increased ADAM-17 activity, as estimated by the ADAM-17 substrates score, was associated with COVID-19 severity (p = 0.001)." (PMID 38892098, 2024). "A study also highlighted the role of ADAM17, a protease involved in the release of these soluble factors into circulation, and its increased activity in severe COVID-19 cases." (PMID 39335653, 2024). "The aim of this study was to investigate if ADAM-17 substrates in plasma are increased in severe COVID-19 and to what extent they are correlated with sACE2." (PMID 38892098, 2024). "It has been recognized that activating the Nrf2 pathway by butyrate releasers reduces COVID-19 severity by inhibiting the ADAM17 pathway." (PMID 37796433, 2023). "These variants were used as instrument variables to examine the effect of circulating ADAM17 on COVID-19, with an average F-statistic of 90 and 30 for the extracellular and cytoplasmic domains, respectively." (PMID 37958866, 2023). "ANG II also aids in cytokine storming in patients with COVID-19 by stimulating ADAM-17 enzymatic activity." (PMID 37372128, 2023). "In agreement with the findings from previous studies, the present study suggests that timely selective inhibition of ADAM17 is a potential therapeutic against severe COVID-19." (PMID 37958866, 2023). "Collectively, these findings indicate that reducing ADAM17 activity has the potential to alleviate the severity of critical COVID-19 cases." (PMID 37958866, 2023). "Collectively, these findings underscore the growing significance of ADAM17 as a pivotal mediator in the context of severe COVID-19." (PMID 37958866, 2023). "The gene expression and functional analysis of the early vs. late COVID-19 cases revealed significant differences with increased levels of ADAM17, C1S, SERPING1, and DDIT3 in the early group." (PMID 35163504, 2022). "Future study on the link between the androgen and the sex difference in the Ace2/Adam17/Tmprss2 complex in COVID-19 and CKD is necessary." (PMID 35887687, 2022). "Understanding the impact of ADAM17 on COVID-19 progression in vivo is paramount to understanding the pathophysiological mechanisms underlying the disease and the development of new therapeutics." (PMID 35757773, 2022). "ADAM17 was substantially overexpressed in blood cells of COVID-19 patients, and more markedly in those patients that ulteriorly experienced a more critical outcome." (PMID 36009555, 2022). "When not inhibited by TIMP-3, due to low SIRT1 activity-mediated TIMP-3 reduction, ADAM17 causes the release of TNF-α and IL6 and contributes to inflammation and possibly to the development of an uncontrolled hyperinflammatory response in COVID-19." (PMID 35457123, 2022). "More recent experimental and clinical data indicate that ACEIs and, particularly, ARBs can be beneficial for COVID-19 outcome, both by reducing inflammatory responses and by triggering mechanisms (such as ADAM17 inhibition) counteracting viral entry." (PMID 35203711, 2022).
COVID-19 (continued). "Soluble ACE2 (sACE2) from ACE2 cleaved by ADAM17 is used as a decoy receptor to trap spikes of virus to prevent cellular engagement for COVID-19 therapy." (PMID 35387343, 2022). "It is of great help to understand the expression of potential SARS-CoV-2 receptors (e.g., ACE2 and ADAM17) in host cells/tissues to reduce the replication and transmission of the virus and the severity of COVID-19." (PMID 36558177, 2022). "Our data are consistent with previous evidence that ADAM17 is a potential therapeutic target for several inflammatory conditions including viral infections (such as COVID-19)." (PMID 34995311, 2022). "Overall, this research not only insinuates the medical significance of ADAM17 for COVID-19 cancer patients, but it also sheds potential light on the treatment of COVID-19." (PMID 36558177, 2022). "For COVID-19 progress, the frequencies of rs4622692 (TG genotype) and rs1048610 (TC genotype) of ADAM17 were significantly higher in the moderate group than in the severe/fatal group." (PMID 36292769, 2022). "To assess this pathway, we blocked the function of ADAM17 using the monoclonal antibody MEDI3622 in the K18-hACE2 transgenic mouse model of COVID-19." (PMID 35757773, 2022). "However, the underlying role of ADAM17 in cancer patients infected with COVID-19 remains unknown." (PMID 36558177, 2022). "A disintegrin and metalloproteinase domain 17 (ADAM17) is another potential target of interest in COVID-19 research." (PMID 35982454, 2022). "This Comment explores the interaction between COVID-19 and cancer with attention paid to the modulation by cancer treatments of both ADAM17 and TMPRSS2, the proteases which control ACE2 processing, the SARS-CoV-2 target." (PMID 33531686, 2021). "In COVID-19, the upregulated activity of ADAM17 increases ACE2 shedding, which in turn leads to higher sACE2 levels, and to the increase of TNF-α production." (PMID 34685735, 2021). "This study evaluated TNF, TNFRs, and ADAM17 at the protein, transcriptional, and gene levels in COVID-19 patients with different levels of disease severity." (PMID 34445140, 2021). "In conclusion, it is clear that ADAM17 plays a crucial and multifactorial role in the development of COVID-19." (PMID 33579029, 2021). "Two health institutions provided the patients, and systematically high solTNFR1 and soluble ADAM17 levels were observed in the severely ill COVID-19 group and patients who died." (PMID 34445140, 2021). "Our results confirm that compared to HD, COVID-19 patients have increased ADAM17 at both proteins (p < 0.0001) and transcriptional levels (p < 0.01)." (PMID 34445140, 2021). "The complex divergent roles of ADAM-17 in AD and potentially COVID-19 require further investigation." (PMID 33380345, 2020). "In the context of COVID-19, the downregulation of ADAM-17 in infected patients could contribute to impaired immune responses, inflammation, and tissue remodeling." (PMID 40003732, 2025). "Given the diverse roles of ADAM17 in the development of COVID-19, this strategy highlights the potential of ADAM17 inhibitors as a promising option for treating COVID-19, emphasizing the need for additional research to assess their effectiveness and safety in clinical settings." (PMID 39292373, 2025). "Dysregulation of the ACE/ACE2 axis by ADAM17 may further impact vascular tone and fluid homeostasis, contributing to complications such as pulmonary hypertension and organ damage in severe COVID-19." (PMID 40725601, 2025). "ADAM-17, on the other hand, showed significant differences (p < 0.05, p < 0.01) between healthy individuals and the other groups, suggesting its potential as a distinguishing marker for COVID-19 impact." (PMID 40003732, 2025). "The findings of the present study contribute to the existing knowledge by indicating that the selective inhibition of ADAM-17 could have potential therapeutic effects in treating COVID-19." (PMID 38892098, 2024).
COVID-19 (continued). "We hypothesized that ADAM-17 substrates in plasma are increased in severe COVID-19, suggestive of increased cellular ADAM-17 activity, and strongly correlated with sACE2." (PMID 38892098, 2024). "There is a lack of studies aiming to assess cellular a disintegrin and metalloproteinase-17 (ADAM-17) activity in COVID-19 patients and the eventual associations with the shedding of membrane-bound angiotensin-converting enzyme 2 (mACE2)." (PMID 38892098, 2024). "In this context, raised sACE2 may also be the result of ADAM-17 overactivation in more severe cases of COVID-19 which leads to an exceeding amount of mACE2 shedding." (PMID 36851081, 2023). "High levels of ADAM17 activity have emerged as an important mediator in severe COVID-19." (PMID 37958866, 2023). "We can only speculate regarding the observed differences between the extracellular and cytoplasmic structural domains of ADAM17 and COVID-19." (PMID 37958866, 2023). "Linking high levels of ADAM17 to increased risk of severe COVID-19 would strengthen the perception that ADAM17 inhibition could be a potential therapeutic target to reduce COVID-19 severity." (PMID 37958866, 2023). "The release of TNF-α through ADAM-17 is essential to COVID-19 pathogenesis." (PMID 37476705, 2023). "Overactivation of ADAM17 activity may be of particular importance in COVID-19, given the direct activation of this protease by the virus." (PMID 37958866, 2023). "Additionally, COVID-19 has been shown to promote ADAM17 expression both at the protein and transcriptional level." (PMID 36851081, 2023). "Therefore, to answer the query of ADAM17′s potential role in severe COVID-19 in humans, it is more relevant to assess the levels of membrane-bound ADAM17 rather than the gene expression of ADAM17." (PMID 37958866, 2023). "Hypothetically, the largest possible number of overlapping samples accounted for 48% of total subjects in the GWAS of ADAM17, 0.8% of subjects in the GWAS of hospitalized COVID-19, 0.7% of subjects for the GWAS of SARS-CoV-2 reported infections and 0% of subjects for GWAS of critical COVID-19." (PMID 37958866, 2023). "However, in contrast to these findings, recent works proved that ADAM17 mRNA and protein were both elevated in severe COVID-19 patients, and ADAM17 inhibition meliorated COVID-19-related lung inflammation." (PMID 36292769, 2022). "However, the ADAM17 expression in different normal tissues and cancer patients, the impacts of ADAM17 on susceptibility for SARS-CoV-2, and the significance for cancer patients in the COVID-19 outbreaks are unclear." (PMID 35720350, 2022). "In this study, we evaluated the ADAM17 inhibitory effects of CD, TQ, and m62A on cancer cells and constructed a visual drug-target-disease network to predict prospective targets and mechanisms of the anti-COVID-19 drugs using network pharmacology." (PMID 36558177, 2022). "Interestingly, when results were analyzed by sex, increases in ADAM17 gene expression in PBCs with both BMI range and COVID-19 severity degree were evidenced in the male patients only." (PMID 36009555, 2022). "Protein-protein interaction results indicated that ADAM17 might play critical roles in the anti-COVID-19 activity of these three compounds." (PMID 36558177, 2022). "Using WES data, we focused on nine genes that have been reported to be involved in the SARS-CoV-2 entry pathway (ACE2, RAB7B, ADAM17, TMPRSS2), host immune response (IFNAR2, TYK2), and/or were previously shown to be associated with COVID-19 outcomes (DPP9, LZTFL1, SLC6A20)." (PMID 36292769, 2022). "Our findings indicate a key contribution by ADAM17 in inflammation regulation during COVID-19." (PMID 35757773, 2022). "In addition, inhibition of ADAM17 can modulate the ACE2 cleavage and the “cytokine storm” typical of COVID-19 and the risk of vascular hyperpermeability, multiorgan failure and death." (PMID 35163482, 2022).
COVID-19 (continued). "ADAM17 mediates shedding of ACE2, IL-6 and TNFα, and suppression of ADAM17 may therefore modulate the cytokine storm that has been identified in patients with severe COVID-19." (PMID 35269582, 2022). "Considering the importance of IL6 in COVID-19-related pathomechanism, anti-IL6 therapies may be effective for severe COVID-19, including selective inhibitors of ADAM-17 or sgp130Fc, which inhibits IL6 signal transduction." (PMID 35165525, 2022). "We found that ADAM17 is also one of the larger nodes, indicating that ADAM17 may play a very important role in the anti-COVID-19 effect of the three compounds." (PMID 36558177, 2022). "The field searching for therapy for COVID-19 is wide, with several open questions; as ADAM17 mediates activation of a vast number of proteins, we propose that solTNFR1 be considered a target in the development of new therapeutic immunomodulation for SARS-CoV2 infection." (PMID 34445140, 2021). "However, despite this evidence indicating a beneficial role for ADAM17 in the pathophysiology of the disease, other investigations have suggested a detrimental role for the protease in development of COVID-19." (PMID 33579029, 2021). "The use of metalloproteinase 17 (ADAM17) or soluble glycoprotein 130 fused chimera (sgp130Fc) to specifically inhibit pathological IL-6 trans-signaling in patients with severe COVID-19 promises to be a more effective and safer strategy to ameliorate disease states." (PMID 33628091, 2021). "The collective effect of TMPRSS2/HAT and ADAM17 on activation of the S protein on COVID-19 and the ACE-2 receptor on type-2 pneumocytes again might be attributable to the high rate of transmission of COVID-19 from person to person." (PMID 34305892, 2021). "ADAM17 level is maintained high at the protein and transcriptional level for each status of COVID-19, but solADAM17 level is higher in severely as compared to mildly ill COVID-19 patients." (PMID 34445140, 2021). "This may contribute to COVID-19 critical illness as overactive ADAM17 can lower the ACE-2 function by generating inactive sACE-2." (PMID 34248502, 2021). "The increase in ADAM17 in the context of COVID-19 may have other implications that might be explored." (PMID 34445140, 2021). "The suppression of ADAM17 may exert a protective effect on COVID-19, since ADAM17 plays an important role in enabling SARS-CoV/CoV-2 to enter host cells through the regulation of the fusion of viral particles with cytoplasmic membranes." (PMID 32930095, 2020). "In this context, the worse clinical outcome observed in COVID-19 patients with diabetes may be due to the exacerbated decline in ACE2 induced by the up-regulation of ADAM17 as consequence of SARS-CoV-2 infection." (PMID 33117379, 2020). "Therefore, targeting ADAM17 presents a dual therapeutic opportunity in the context of COVID-19 which can help to modulate the inflammatory response and alleviate the cytokine storm associated with severe disease, but also to impede SARS-CoV-2 entry and propagation." (PMID 39292373, 2025). "Moreover, ADAM17-mediated shedding of pro-inflammatory cytokines and other immune-modulatory molecules contributes to the pathogenesis of inflammatory diseases, including COVID-19." (PMID 39292373, 2025). "Thus, RNAseq data obtained from the myocardial tissues of COVID-19 patients showed an association between the expression of ACE2, ADAM17, and other potential accessory proteases in pericytes and fibroblasts that might facilitate SARS-CoV-2 infection." (PMID 38474396, 2024). "Additionally, differences in ACE2 and ADAM-17 gene expressions between different tissues may be of importance in explaining why the lung is the organ most severely affected by COVID-19, but this requires further evaluation in prospective studies." (PMID 38892098, 2024). "In contrast, we did not observe any causal effect of COVID-19 on circulating ADAM17 levels." (PMID 37958866, 2023).